WDR38 (WD repeat domain 38)
Tractability: No criterion of Open Targets' tractability assessment is met for any kind of drug.
Gene: Protein-coding gene on chromosome 9 (124,853,266 to 124,859,132, forward strand). Ensembl gene ENSG00000136918.
Subcellular location (Human Protein Atlas): Vesicles
Gene Ontology:
Biological process: regulation of transcription by RNA polymerase II
Cellular component: nucleus
Genetic constraint (gnomAD): Loss-of-function variants: 37 observed, 36.89 expected, observed/expected ratio (o/e) 1, 90% interval 0.77 to 1.32. The upper end of that interval is the gene's LOEUF score, 1.32, which puts it in group 5 of 6, group 1 being the genes least tolerant of losing a copy. Missense variants: 411 observed, 418.72 expected, observed/expected ratio (o/e) 0.98, 90% interval 0.9 to 1.07. Synonymous variants: 164 observed, 168.49 expected, observed/expected ratio (o/e) 0.97, 90% interval 0.86 to 1.11.
Homologues: Orthologues: chimpanzee WDR38 (99% identical), macaque WDR38 (96% identical), rabbit WDR38 (80% identical), pig WDR38 (78% identical), mouse Wdr38 (73% identical), rat Wdr38 (70% identical), dog WDR38 (67% identical). Paralogues in human: TEP1 (28% identical), WDR17 (25% identical), WDR5 (23% identical), WDR5B (23% identical), POC1A (22% identical), POC1B (22% identical), WDR7 (21% identical), AHI1 (20% identical), SNRNP40 (19% identical), WDR62 (18% identical), DAW1 (18% identical), MAPKBP1 (17% identical), and 14 more.
Diseases named in the same sentence as WDR38 in open-access papers:
WDR38 is named in the same sentence as 1 disease in open-access papers, as found by Europe PMC text mining. Sharing a sentence is not in itself a finding about the gene and the disease.
WDR38 shares sentences with these, for which no sentence is quoted: carcinosarcoma (1 paper).